HIVEP1 (HIVEP zinc finger 1)
Description:
This protein specifically binds to the DNA sequence 5'-GGGACTTTCC-3' which is found in the enhancer elements of numerous viral promoters such as those of SV40, CMV, or HIV-1. In addition, related sequences are found in the enhancer elements of a number of cellular promoters, including those of the class I MHC, interleukin-2 receptor, and interferon-beta genes. It may act in T-cell activation. Involved in activating HIV-1 gene expression. Isoform 2 does not activate HIV-1 gene expression. Isoform 2 and isoform 3 may be involved in apoptosis.
Synonyms: CIRIP; GAAP; MBP-1; PRDII-BF1; ZNF40; CRYBP1; ZAS1; Schnurri-1; ZNF40A
Tractability: PROTAC: ubiquitination databases record sites on it.
Target class: Transcription factor
Gene: Protein-coding gene on chromosome 6 (12,008,762 to 12,164,999, forward strand). Ensembl gene ENSG00000095951.
Subcellular location: Nucleus (Isoform 1); Cytoplasm (Isoform 2); Nucleus; Cytoplasm (Isoform 3)
Subcellular location (Human Protein Atlas): Nucleoplasm; Cytosol; Mitochondria; Nuclear bodies
Gene Ontology:
Molecular function: protein binding; sequence-specific double-stranded DNA binding; DNA-binding transcription factor activity, RNA polymerase II-specific; RNA polymerase II cis-regulatory region sequence-specific DNA binding; DNA binding; DNA-binding transcription repressor activity, RNA polymerase II-specific
Biological process: BMP signaling pathway; negative regulation of transcription by RNA polymerase II; positive regulation of transcription by RNA polymerase II; regulation of transcription by RNA polymerase II; negative regulation of DNA-templated transcription
Cellular component: cytosol; nuclear body; nucleoplasm; nucleus; cytoplasm
Genetic constraint (gnomAD): Loss-of-function variants: 27 observed, 161.46 expected, observed/expected ratio (o/e) 0.17, 90% interval 0.12 to 0.23. The upper end of that interval is the gene's LOEUF score, 0.23, which puts it in group 1 of 6, group 1 being the genes least tolerant of losing a copy. Missense variants: 2,991 observed, 3,237.6 expected, observed/expected ratio (o/e) 0.92, 90% interval 0.9 to 0.95. Synonymous variants: 1,182 observed, 1,238.5 expected, observed/expected ratio (o/e) 0.95, 90% interval 0.91 to 1.
Homologues: Orthologues: chimpanzee HIVEP1 (99% identical), macaque HIVEP1 (95% identical), dog HIVEP1 (80% identical), pig HIVEP1 (76% identical), guinea pig HIVEP1 (74% identical), rat Hivep1 (71% identical), mouse Hivep1 (71% identical), rabbit HIVEP1 (69% identical), tropical clawed frog hivep1 (48% identical), zebrafish hivep1 (42% identical). Paralogues in human: HIVEP2 (25% identical), HIVEP3 (24% identical), ZNF831 (13% identical), RREB1 (10% identical), SALL3 (7% identical), SALL1 (7% identical), SALL4 (6% identical), BCL11B (5% identical), BCL11A (5% identical), ZNF516 (5% identical), ZNF536 (5% identical), SALL2 (4% identical), and 2 more.
Diseases named in the same sentence as HIVEP1 in open-access papers:
HIVEP1 is named in the same sentence as 13 diseases in open-access papers, as found by Europe PMC text mining. Sharing a sentence is not in itself a finding about the gene and the disease. The quoted sentences say what the papers report.
venous thromboembolism (2 papers, 2024 to 2025). Occlusion of the lumen of a vein by a thrombus that has migrated from a distal site via the blood stream. "In addition, plasma HIVEP1 level is positively associated with the occurrence of venous thromboembolism." (PMID 38231044, 2024). "Von Willebrand factor (vWF), PDGFB, HIVEP1, and GPX3 have been identified as biomarkers associated with venous thromboembolism in the VEBIOS cohort, with the associations of vWF and PDGFB replicated in FARIVE." (PMID 39940903, 2025).
Venous thrombosis (2 papers, 2021 to 2024). Formation of a blood clot (thrombus) inside a vein, causing the obstruction of blood flow. "Increased endothelial HIVEP1 has been linked to elevated endothelial platelet adhesion, and genetic variants at the HIVEP1 locus are associated with venous thrombosis." (PMID 38231044, 2024). "Interestingly, genetic variation at the HIVEP1 locus was associated with an increased risk for venous thrombosis and enhanced inflammation has been implicated in the pathogenesis of thrombosis." (PMID 34804025, 2021).
bacterial sepsis (1 paper, 2021). "To study the role of HIVEP1 during bacterial sepsis in vivo, we treated zebrafish embryos with antisense morpholinos directed against HIVEP1 or a mismatch control morpholino prior to systemic infection with Streptococcus (S.)pneumoniae." (PMID 34804025, 2021).
HIV-1 infection (1 paper, 2010). The type species of lentivirus and the etiologic agent of acquired immunodeficiency syndrome (AIDS). "It is not surprising that a transcription factor such as HIVEP1 would be present during HIV-1 infection; however, the identification of this protein is not necessarily a marker for a LTNP phenotype." (PMID 20604950, 2010).
ischemic stroke (1 paper, 2025). A stroke disorder caused by obstruction of blood flow to the brain, due to thrombotic (local blood clot formation) or embolic (due to a blood clot or other material traveling from another site) event. "Although the exact functional consequences of F11 rs4253417 and HIVEP1 rs169713 remain unclear, F11 encodes coagulation factor XI, suggesting that variants in this gene may influence plasma FXI levels and modulate thrombosis risk, as previously identified in patients with ischemic stroke." (PMID 41440514, 2025).
Obesity (1 paper, 2022). Accumulation of substantial excess body fat. "NEDD9 was found to regulate the developing embryonic nervous system, and HIVEP1 was involved in the obesity of newborns." (PMID 36685960, 2022).
Sepsis (1 paper, 2021). Sepsis is defined as life-threatening organ dysfunction caused by a dysregulated host response to infection. "In conclusion, we here demonstrate that HIVEP1 acts as repressor of NF-kB activity induced by bacterial agonists and that HIVEP1 deficiency exacerbates inflammation in sepsis." (PMID 34804025, 2021). "Inhibition of cytokine production by HIVEP1 was confirmed in LPS-stimulated murine Hivep1-/- macrophages and HIVEP1 knockdown zebrafish exposed to the common sepsis pathogen Streptococcus pneumoniae." (PMID 34804025, 2021). "Inhibition of cytokine production by HIVEP1 was confirmed in LPS-stimulated murine Hivep1-/- macrophages in vitro and in HIVEP1 knockdown zebrafish exposed to the common sepsis pathogen S. pneumoniae in vivo." (PMID 34804025, 2021). "We here report enhanced HIVEP1 mRNA expression in monocytes from patients with sepsis, as well as monocytes stimulated by a variety of TLR agonists and bacteria." (PMID 34804025, 2021). "The primary objective of the current study was to investigate the functional role of HIVEP1 in the response of monocytes to bacterial agonists in vitro and during experimental sepsis in vivo." (PMID 34804025, 2021). "We report increased HIVEP1 mRNA expression in monocytes from patients with sepsis and monocytes stimulated by Toll-like receptor agonists and bacteria." (PMID 34804025, 2021). "Patients with sepsis due to community-acquired pneumonia showed increased HIVEP1 mRNA expression in peripheral blood mononuclear cells purified from blood obtained within 24 hours after admission to the Intensive Care Unit, when compared with those from healthy controls." (PMID 34804025, 2021).
infection (2 papers, 2011 to 2021). The state of being infected such as from the introduction of a foreign agent such as serum, vaccine, antigenic substance or organism. "The immune function and chromatin remodelling family of GATA transcription factors are associated by the inclusion of SNPs near HIVEP1 (rs10755709), which encodes a viral-infection regulation transcription factor, and GATA3 (rs71481792)." (PMID 34210368, 2021).
HIVEP1 also shares sentences with these, for which no sentence is quoted: tumor (2 papers); nonsmall cell lung cancer (1); osteosarcoma (1); thrombosis (1); viral infection (1).